ACAN (aggrecan)
Description:
This proteoglycan is a major component of extracellular matrix of cartilagenous tissues. A major function of this protein is to resist compression in cartilage. It binds avidly to hyaluronic acid via an N-terminal globular region.
Synonyms: AGC1; CSPG1; MSK16; CSPGCP; AGCAN; SEDK; SSOAOD
Tractability: Antibody: its Gene Ontology location is reachable by antibodies, with high confidence; UniProt places it where antibodies can reach, with medium confidence; UniProt predicts a signal peptide or a membrane-spanning region.
Gene: Protein-coding gene on chromosome 15 (88,803,436 to 88,875,353, forward strand). Ensembl gene ENSG00000157766.
Subcellular location: Secreted, extracellular space, extracellular matrix
Pathways (Reactome):
Disease: Defective B4GALT1 causes B4GALT1-CDG (CDG-2d); Defective CHST6 causes MCDC1; Defective ST3GAL3 causes MCT12 and EIEE15
Extracellular matrix organization: Degradation of the extracellular matrix; ECM proteoglycans
Metabolism: Keratan sulfate biosynthesis; Keratan sulfate degradation
Gene Ontology:
Molecular function: protein binding; extracellular matrix structural constituent; extracellular matrix structural constituent conferring compression resistance; hyaluronic acid binding
Biological process: central nervous system development; proteolysis; skeletal system development; cell adhesion
Cellular component: extracellular matrix; extracellular region; gel phase of interstitial matrix; Golgi lumen; lysosomal lumen; perineuronal net; synapse; basement membrane; GABA-ergic synapse; glutamatergic synapse; perisynaptic extracellular matrix
Genetic constraint (gnomAD): Loss-of-function variants: 46 observed, 155.89 expected, observed/expected ratio (o/e) 0.3, 90% interval 0.23 to 0.38. The upper end of that interval is the gene's LOEUF score, 0.38, which puts it in group 1 of 6, group 1 being the genes least tolerant of losing a copy. Missense variants: 2,656 observed, 2,701.6 expected, observed/expected ratio (o/e) 0.98, 90% interval 0.95 to 1.01. Synonymous variants: 1,093 observed, 1,096.6 expected, observed/expected ratio (o/e) 1, 90% interval 0.95 to 1.05.
Gene-disease validity (ClinGen):
ClinGen rates the evidence that ACAN causes each of these diseases.
ACAN-related short stature spectrum (autosomal dominant): Definitive.
Homologues: Orthologues: chimpanzee ACAN (88% identical), macaque ACAN (81% identical), pig ACAN (72% identical), dog ACAN (71% identical), rabbit ACAN (64% identical), rat Acan (64% identical), mouse Acan (64% identical), guinea pig ACAN (64% identical), zebrafish acana (26% identical), zebrafish acanb (23% identical). Paralogues in human: VCAN (24% identical), NCAN (15% identical), BCAN (14% identical), HAPLN3 (5% identical), HAPLN1 (5% identical), HAPLN4 (5% identical), HAPLN2 (4% identical).
Diseases named in the same sentence as ACAN in open-access papers:
ACAN is named in the same sentence as 199 diseases in open-access papers, as found by Europe PMC text mining. Sharing a sentence is not in itself a finding about the gene and the disease. The quoted sentences say what the papers report.
osteoarthritis (141 papers, 2006 to 2026). A noninflammatory degenerative joint disease occurring chiefly in older persons, characterized by degeneration of the articular cartilage, hypertrophy of bone at the margins and changes in the synovial membrane. "Aggrecan degradation is a hallmark of degenerative musculoskeletal disorders and has been extensively studied in osteoarthritis." (PMID 40806719, 2025). "Aggrecan is responsible for the viscoelastic properties of articular cartilage and its degradation is a major hallmark of degenerative joint diseases such as osteoarthritis (OA) and rheumatoid arthritis (RA)." (PMID 39600538, 2024). "Neomorphic and hypomorphic mutations in ACAN are associated with short stature, early onset of osteoarthritis and multiple spinal abnormalities." (PMID 36937743, 2023). "One of the early hallmarks of osteoarthritis (OA) is the loss of aggrecan from articular cartilage followed by degeneration of the tissue." (PMID 35585042, 2022). "Scutellarin alleviates Col-2 and aggrecan loss in chondrocytes during the development of osteoarthritis." (PMID 36032701, 2022). "We previously reported a missense ACAN variant linked to familial osteochondritis dissecans, with short stature and early onset osteoarthritis, and now describe three novel ACAN gene variants from additional families with this disorder." (PMID 35338222, 2022). "Loss of aggrecan is an early pathological feature of cartilage matrix breakdown that occurs in osteoarthritis (OA), a disease estimated to affect over 250 million people worldwide, and a leading cause of disability and societal burden." (PMID 34423304, 2021). "Loss of aggrecan in late-stage osteoarthritis prevents growth factor release and likely contributes to disease progression." (PMID 34423304, 2021). "Aggrecan is a major component of articular cartilage, and its uncontrolled degradation can cause degenerative joint diseases." (PMID 33804223, 2021). "We report a novel ACAN heterozygous pathogenic variant in a family with idiopathic short stature, early-onset osteoarthritis and osteoarthritis dissecans (SSOAOD)." (PMID 34456977, 2021). "COL2A1 and ACAN genes are directly associated with the Osteoarthritis pathway, which are represented by the solid lines, while COL1 and SOX6 are not, which are represented by the dotted lines." (PMID 34970658, 2019). "In conclusion, our data demonstrate that Agc1CreERT2/CreERT2 mice have smaller skeleton, stiffer articular cartilage and are prone to spontaneous, age-associated osteoarthritis owing to reduced deposition of aggrecan in cartilage." (PMID 30813547, 2019). "We found that reduced aggrecan leads to increased stiffness of the articular cartilage, which in turn results in severe age-associated osteoarthritis." (PMID 30813547, 2019). "Osteoarthritis (OA), a joint disease caused by cartilage loss, is strongly associated with a net loss of aggrecan and collagen breakdown caused by an imbalance in ECM homeostasis." (PMID 27460424, 2016). "Changes in the content of aggrecan, an essential proteoglycan of articular cartilage, have been implicated in the pathophysiology of osteoarthritis (OA), a prevalent age‐related, degenerative joint disease." (PMID 26910618, 2016). "Serum levels of KS have been reported as an indirect measure of aggrecan turnover in articular cartilage and further analyzed for a role as a predisposing factor for osteoarthritis (OA) with a polyarticular, progressive phenotype." (PMID 22629396, 2012). "Children with ACAN mutations may develop early-onset joint pain or osteoarthritis, while variants in COL2A1 or FLNB may lead to orthopedic complications." (PMID 40723048, 2025). "Cartilage degradation starts with aggrecan loss in osteoarthritis (OA)." (PMID 39275306, 2024).
osteoarthritis (continued). "The excess ROS and related oxidative stress are correlated with the progression of osteoarthritis, characterized by the changes in the hyaline cartilage markers, i.e., an increased catabolism of proteoglycan aggrecan (ACAN) and a loss of type II collagen (COL2A1)." (PMID 36230915, 2022). "However, of the 12 adult individuals with ACAN variants, 5 cases developed osteoarthritis or intervertebral disc diseases." (PMID 35330881, 2022). "The degradation of aggrecan is an important event in early osteoarthritis, suggesting that inhibition of the loss of condensed polysaccharides may be curative for early osteoarthritis." (PMID 35883515, 2022). "Mice with a mutation that rendered aggrecan resistant to the action of ADAMTS proteases at the E373- A374 site were protected from surgically induced osteoarthritis and inflammatory arthritis, indicating that ADAMTS proteases were major instruments of articular cartilage breakdown in arthritis." (PMID 34195596, 2021). "Furthermore, aggrecan degradation is a hallmark of cartilage degeneration occurring in osteoarthritis." (PMID 30813547, 2019). "First, the ACAN gene encodes a major component of the extracellular matrix, lending important biomechanical properties of cartilage, which explains its role in diseases such as osteoarthritis (MIM: 155760)." (PMID 29362361, 2018). "Guava leaf extract and ellagic acid, one of its polyphenolic components, inhibit the activity of a disintegrin and metalloproteinase with thrombospondin type 5 (ADAMTS‐5), which is associated with aggrecan degeneration during the early stage of osteoarthritis (OA)." (PMID 29983942, 2018). "Furthermore, knock-in mice with a mutation in the interglobular domain of aggrecan that are resistant to cleavage by aggrecanase are protected from cartilage erosion in surgically induced osteoarthritis." (PMID 28270508, 2017). "A hallmark of osteoarthritis is increased proteolytic cleavage of aggrecan." (PMID 28679445, 2017). "Aggrecan degradation is the hallmark of cartilage degeneration in osteoarthritis (OA), though it is unclear whether a common proteolytic process occurs in all individuals." (PMID 26891838, 2016). "For comprehensiveness considerations, advanced bone age and osteoarthritis do occur in a certain proportion of patients with short stature, caused by ACAN variants, which could contribute to disease diagnosis; however, they are not obligatory conditions for making the diagnosis." (PMID 35330881, 2022). "Intriguingly, IMB-R38 treatment significantly increased the Aggrecan mRNA level compared with the model group, suggesting its therapeutic potential for osteoarthritis, although further investigation is required." (PMID 41465573, 2025). "Due to its role in removing aggrecan in the progression of osteoarthritis (OA), ADAMTS-5 is often regarded as a potential therapeutic target for OA." (PMID 40362332, 2025). "Aggrecan, a crucial structural protein within the extracellular matrix of cartilage, undergoes degradation in osteoarthritis." (PMID 41465573, 2025). "The Adam10 protein, which degrades aggrecan, is increased in degenerated cartilage and osteoarthritis cartilage." (PMID 37525533, 2023). "In particular, CNPs promoted the expression of genes involved in collagen (COL1A1 and COL2A1) and aggrecan (ACAN) deposition, phenomena that are strongly impaired in osteoarthritis." (PMID 37887953, 2023). "ADAMTS5 is an aggrecanase that cleaves aggrecan, a major proteoglycan of cartilage, and mediate cartilage destruction in osteoarthritis." (PMID 36805735, 2023). "Aggrecan is the most abundant proteoglycan in articular cartilage, and its degradation has a central role in the pathogenesis of osteoarthritis (OA)." (PMID 37426292, 2023). "Meanwhile, Aggrecan Cre mice have been used by others to examine postnatal phenotypes such as osteoarthritis." (PMID 38042486, 2023).
osteoarthritis (continued). "Similar conclusions were reached by Maldonado and Nam, who indicated that aggrecan and collagen degradation was an important event in the early stages of osteoarthritis." (PMID 38136608, 2023). "Aggrecan plays a key role in bearing compressive loads in articular cartilage, and aggrecan fragments are released into the synovial fluid under osteoarthritis conditions." (PMID 37189729, 2023). "Further, other ECM components such as PGs, HA, aggrecan and glycoproteins seem to be useful tools for osteoarthritis diagnosis." (PMID 36342580, 2023). "Members of the ADAMTS (a disintegrin and metalloproteinase with thrombospondin motifs) family, mainly ADAMTS-4 and ADAMTS-5, are major aggrecan-degrading enzymes in osteoarthritis." (PMID 36362216, 2022). "In this paper we describe three novel missense ACAN gene variants in families with hereditary OCD, short stature and early onset osteoarthritis." (PMID 35338222, 2022). "Runx3-knockout mice exhibited accelerated osteoarthritis following surgical induction, accompanied by decreased expression of lubricin and aggrecan." (PMID 36261443, 2022). "Destruction of articular cartilage in osteoarthritis (OA) is initiated by depletion of the hyaluronan (HA)-aggrecan network, followed by degradation of the collagen fibrils." (PMID 36241903, 2022). "Molecules involved in cartilage degeneration, or being markers of inflammation in osteoarthritis, are cytokines, such as tumor necrosis factor α (TNFα), interleukins (IL), type II collagen, aggrecan, and metalloproteinases." (PMID 35406644, 2022). "Mediators associated with inflammation and joint strain degrade the aggrecan, with the presence of aggrecan fragments as a marker of ongoing cartilage destruction in osteoarthritis." (PMID 36077525, 2022). "To investigate how FA impacted IL‐1β‐induced osteoarthritis chondrocyte degeneration, we examined chondrocyte de‐differentiation markers collagen I and Runx‐2 and chondrogenic genes including collagen II and aggrecan." (PMID 34078001, 2021). "In vitro and in vivo studies showed that the accumulated doses of nicotine significantly suppressed chondrocytes and chondrogenic markers (Sox, type II collagen, and aggrecan); hence, delaying chondrogenesis and inducing osteoarthritis." (PMID 34671637, 2021). "The relationship between ADAMTSs and aggrecan was explored not only in pathologies like degenerative joint diseases but also in vascular alterations." (PMID 33804223, 2021). "TNFα levels are increased in the synovial fluid of patients with osteoarthritis and rheumatoid arthritis and reduce the expression of Col2a1, Acan (Aggrecan), and Hapln1 through EGR1 recruitment to their promoters." (PMID 32121305, 2020). "Osteoarthritis (OA) is associated with cartilage breakdown, brought about by ADAMTS-5 mediated aggrecan degradation followed by MMP-derived aggrecan and type II collagen degradation." (PMID 32825512, 2020). "HIF-2α downstream degradation factors, such as MMP-3,13 and ADAMTs-4,5, played essential roles in the degradation of cartilage aggrecan and had been recognized as one of the most primary targets for therapeutic intervention in osteoarthritis." (PMID 32083119, 2019). "We have designed an aggrecan mimetic that is composed of chondroitin sulfate decorated with HA-binding peptides in an effort to mimic key aggrecan function for the treatment of osteoarthritis." (PMID 32082161, 2019). "Previous studies have demonstrated that asporin interacts directly with TGF-β1 and inhibits downstream gene expression of aggrecan and collagen in osteoarthritis." (PMID 31608236, 2019). "These aggrecan mimetics have been shown to penetrate aggrecan-depleted cartilage, contribute to its overall compressive strength, and reduce catabolic activity in in vivo and ex vivo models of osteoarthritis." (PMID 32082161, 2019).
osteoarthritis (continued). "We transfected human osteoarthritis chondrocytes with an miR-448 mimic or inhibitor, expressions of matrilin-3, aggrecan, type II collagen and MMP-13 were determined using western blot, quantitative real-time PCR and ELISA assays as appropriate." (PMID 29483929, 2018). "Once aggrecan was degraded, elasticity of the articular cartilage was disappeared, and the joint shows similar condition to the initial stage of osteoarthritis." (PMID 29137610, 2017). "Aggrecanase-mediated aggrecan degeneration is also a key and critical event in initial-stage osteoarthritis." (PMID 29137610, 2017). "These enzymes cleave the aggrecanase-specific Glu373-Ala374 bond in the interglobular domain region of aggrecan core protein, and are deeply involved in the pathology of arthritic joint diseases such as osteoarthritis." (PMID 29137610, 2017). "Structural heterogeneity was analyzed in aggrecan isolated from 34 individuals, including 11 males and 23 females, ranging in age from 46 to 89 years at the time of total knee replacement for osteoarthritis." (PMID 26891838, 2016). "ADAMTS (a disintegrin and metalloproteinase with thrombospondin motifs) family is known to play an important role in the pathogenesis of osteoarthritis (OA), working on aggrecan degradation or altering the integrity of extracellular matrix (ECM)." (PMID 26818776, 2016). "The ECM enzyme ADAMTS5, a member of the ADAMTS (A Disintegrin-like and Metalloproteinase with Thrombospondin-1 motifs) protein family, cleaves large proteoglycans such as aggrecan, leading to the destruction of cartilage and osteoarthritis." (PMID 27855162, 2016). "For example, osteoarthritis is characterized by degradation of type II collagen and aggrecan by collagenolytic MMPs and aggrecan-degrading ADAMTSs, respectively." (PMID 27582494, 2016). "Here, we examined the effect of SOX9 acetylation on ACAN transactivation in the context of osteoarthritis." (PMID 26910618, 2016). "The presence of increased levels of aggrecan fragments in synovial fluid has been used as a marker of ongoing cartilage destruction in osteoarthritis." (PMID 26914753, 2014). "Aggrecanase mediated degradation of aggrecan is known to play a significant role in the development of osteoarthritis (OA)." (PMID 24967368, 2014). "They show some osteoarthritis-like changes in cartilage such as a decreased level of aggrecan and link protein 1, a rapid catabolism of aggrecan, and abnormally aggregated and disarranged type-II collagen fibers." (PMID 22952769, 2012). "Osteoarthrosis is characterized by cartilage erosion, proteolysis of aggrecan and collagen, and disturbed rates of synthesis of aggrecan and hyaluronan by chondrocytes, with hyaluronan over-production being an early reaction." (PMID 18205921, 2008). "This leucine-rich repeat protein was shown to interact with and inhibit TGFβ signaling which is thought to lead to insufficient quantities of aggrecan and type II collagen in osteoarthritis." (PMID 17389037, 2007). "By binding aggrecan to stable complexes, HA helps protect aggrecan from enzymatic degradation owing to the effects of enzymes typical of osteoarthritis, such as aggrecanases and matrix metalloproteinases (MMPs), which are elevated and degrade ECM components, including aggrecan." (PMID 40283379, 2025). "ADAMTS4-mediated aggrecan degradation in articular cartilage is widely recognized as a primary etiological factor in the pathogenesis of osteoarthritis, while its cleavage of both aggrecan and versican plays a crucial role in the instability of atherosclerotic plaques." (PMID 40002887, 2025). "In an osteoarthritis chondrocyte model, Lys improved the hypertrophic transformation of chondrocytes by modulating matrix proteins and inflammatory cytokines by restoring collagen (type II collagen/type I collagen ratio) and aggrecan expression levels." (PMID 40559419, 2025).